ARG1 (arginase 1)
Description:
Key element of the urea cycle converting L-arginine to urea and L-ornithine, which is further metabolized into metabolites proline and polyamides that drive collagen synthesis and bioenergetic pathways critical for cell proliferation, respectively; the urea cycle takes place primarily in the liver and, to a lesser extent, in the kidneys. Functions in L-arginine homeostasis in nonhepatic tissues characterized by the competition between nitric oxide synthase (NOS) and arginase for the available intracellular substrate arginine. Arginine metabolism is a critical regulator of innate and adaptive immune responses. Involved in an antimicrobial effector pathway in polymorphonuclear granulocytes (PMN). Upon PMN cell death is liberated from the phagolysosome and depletes arginine in the microenvironment leading to suppressed T cell and natural killer (NK) cell proliferation and cytokine secretion. In group 2 innate lymphoid cells (ILC2s) promotes acute type 2 inflammation in the lung and is involved in optimal ILC2 proliferation but not survival (By similarity). In humans, the immunological role in the monocytic/macrophage/dendritic cell (DC) lineage is unsure.
Tractability: Small molecule: a structure with a bound ligand is known; a high-quality ligand is known; it has a binding pocket of medium quality. Antibody: its Gene Ontology location is reachable by antibodies, with high confidence. PROTAC: ubiquitination databases record sites on it; its protein half-life has been measured; a small molecule that binds it is known.
Target class: Enzyme; Hydrolase
Gene: Protein-coding gene on chromosome 6 (131,470,832 to 131,584,332, forward strand). Ensembl gene ENSG00000118520.
Subcellular location: Cytoplasm; Cytoplasmic granule
Pathways (Reactome):
Disease: ARG1 variants cause hyperargininemia
Immune System: Neutrophil degranulation
Metabolism: Urea cycle
Gene Ontology:
Molecular function: arginase activity; protein binding; manganese ion binding; hydrolase activity, acting on carbon-nitrogen (but not peptide) bonds, in linear amidines; metal ion binding
Biological process: L-arginine catabolic process; negative regulation of T cell proliferation; negative regulation of type II interferon-mediated signaling pathway; neutrophil-mediated killing of fungus; urea cycle; arginine metabolic process; defense response to protozoan; negative regulation of activated T cell proliferation; negative regulation of T-helper 2 cell cytokine production; regulation of cell population proliferation
Cellular component: cytoplasm; extracellular region; nucleus; azurophil granule lumen; cytosol; specific granule lumen
Genetic constraint (gnomAD): Loss-of-function variants: 21 observed, 36.3 expected, observed/expected ratio (o/e) 0.58, 90% interval 0.41 to 0.83. The upper end of that interval is the gene's LOEUF score, 0.83, which puts it in group 3 of 6, group 1 being the genes least tolerant of losing a copy. Missense variants: 374 observed, 406.34 expected, observed/expected ratio (o/e) 0.92, 90% interval 0.85 to 1. Synonymous variants: 146 observed, 148.77 expected, observed/expected ratio (o/e) 0.98, 90% interval 0.86 to 1.13.
Gene-disease validity (ClinGen):
ClinGen rates the evidence that ARG1 causes each of these diseases.
arginase deficiency (autosomal recessive): Definitive. Arginase deficiency is a rare autosomal recessive amino acid metabolism disorder characterized clinically by variable degrees of hyperammonemia, developing from about 3 years of age, and leading to progressive loss of developmental milestones and spasticity in the absence of treatment.
Homologues: Orthologues: chimpanzee ARG1 (99% identical), macaque ARG1 (98% identical), rabbit ARG1 (91% identical), dog ARG1 (90% identical), rat Arg1 (87% identical), mouse Arg1 (87% identical), pig ARG1 (86% identical), guinea pig ARG1 (85% identical), tropical clawed frog arg1 (70% identical), zebrafish arg1 (62% identical), Drosophila melanogaster arg (39% identical). Paralogues in human: ARG2 (59% identical), AGMAT (25% identical).
Diseases named in the same sentence as ARG1 in open-access papers:
ARG1 is named in the same sentence as 410 diseases in open-access papers, as found by Europe PMC text mining. Sharing a sentence is not in itself a finding about the gene and the disease. The quoted sentences say what the papers report.
breast cancer (69 papers, 2014 to 2026). A primary or metastatic malignant neoplasm involving the breast. "RON-deficient macrophages in mammary tumors showed increased iNOS and decreased arginase-1 expression as compared to wild-type RON macrophages." (PMID 40282397, 2025). "M-MDSCs in breast cancer express arginase-1 (ARG1; encoded ARG1) and iNOS, which deplete L-arginine and produce nitric oxide, respectively." (PMID 41550427, 2025). "Arg1, a hydrolase enzyme involved in the breakdown of L-arginine, has been shown to accumulate in human and murine breast cancer, and its presence is associated with poor prognosis and an enhanced immunosuppressive environment." (PMID 39195207, 2024). "Our findings highlight the potential use of ARG1-positive myeloid cells as an independent prognostic marker to evaluate the risk of metastasis in breast cancer patients." (PMID 37980483, 2023). "In our pursuit to understand the role of myeloid cells in metastatic breast cancer, we found an association between the presence of infiltrating ARG1-positive myeloid cells and aggressive tumour features in both breast cancer mouse models and patients." (PMID 37980483, 2023). "Pearson’s χ2 test was used to assess the association between ARG1 protein expression in human breast cancer tissues and different patient and tumour characteristics." (PMID 37980483, 2023). "To assess the translational relevance of our in vivo findings, we assessed human breast cancer biopsies and evaluated the association between arginase 1 protein expression in breast cancer tissues with tumour characteristics and patient outcomes." (PMID 37980483, 2023). "Through xenograft models, we demonstrated that co-transplantation with DCIS fibroblasts enhanced breast cancer growth and invasion associated with increased recruitment of arginase-1+ cells." (PMID 37091166, 2023). "Grafting studies in mice revealed that DCIS fibroblasts enhanced breast cancer growth and invasion associated with arginase-1+ cell recruitment." (PMID 37091166, 2023). "Overexpression of Arg-1 has been linked to poor prognosis in certain cancers, including colorectal cancer and breast cancer." (PMID 34715880, 2021). "Several known MDSC-associated genes were highly up regulated in breast cancer/sepsis monocytes when compared with healthy controls, including e.g. ARG1 and S100A12." (PMID 25992611, 2015). "Moreover, in human breast cancer patients a higher number of ARG1-positive infiltrating cells was associated with a high histopathological grade and proliferation." (PMID 37980483, 2023). "Arg1 is commonly expressed by immune inhibitory cells, such as tumor-associated macrophages and myeloid derived suppressor cells, as well as by a diversity of tumor cells, including breast cancer." (PMID 33378681, 2020). "GM-CSF, another cytokine, is known to facilitate the development of the immunosuppressive breast cancer microenvironment by regulating myeloid cell ARG1 expression." (PMID 41491244, 2026). "The current study revealed that a combination of GEN supplementation and moderate-intensity exercise increased the M1 macrophage marker CD68 while reducing M2 macrophage markers CD163 and Arg1 in breast cancer tissue." (PMID 40604704, 2025). "It has been shown that breast cancer-derived CSF2 regulates Arg1 to promote an immunosuppressive TME." (PMID 39996058, 2025). "In examining the TME, mammary tumors from MMTV-RONHGFL−/− mice exhibited increased infiltration of F4/80 positive macrophages but also a significant decrease in Arginase 1 staining and a corresponding increase in iNOS staining." (PMID 40282397, 2025). "Global HGFL loss in the PyMTHGFL−/− mouse model also led to an increase in CD8a T cells, F4/80+ and iNOS+ macrophages, and decreased Arginase-1 macrophages in mammary tumors." (PMID 40282397, 2025).
breast cancer (continued). "GM‐CSF derived from breast tumor cells can promote the development of an immunosuppressive breast cancer microenvironment by regulating the expression of myeloid cell ARG1 and can also enhance immunotherapy for breast cancer." (PMID 40717900, 2025). "The elevation of Arg1 expression has been observed in TAMs from an early-stage mammary tumor mouse model and in circulating myeloid cells of patients with BC." (PMID 39371092, 2024). "PDE5 inhibition can reduce iNOS and Arg1 activity in MDSCs, thereby triggering antitumor response and T cell infiltration in preclinical models of colon cancer and breast cancer or in patients with end-stage multiple myeloma." (PMID 38226622, 2024). "Doxorubicin is routinely used for breast cancer treatment in patients as a chemotherapeutic agent, and mechanistically reduces expression of MDSC-associated genes including Arg1, iNOS, S100A8 and S100A9 in breast tumour mouse models." (PMID 38464388, 2024). "The targeted therapy drug cabozantinib which inhibits multiple receptor tyrosine kinases has been shown to reduce MDSC Arg1 expression and frequency by 20%, 0.8% and 35% in the tumour microenvironment, lymph nodes and spleen respectively in breast cancer mice." (PMID 38464388, 2024). "Recent mouse breast cancer model studies suggest that carcinoma cell-derived GM-CSF acts to promote an immunosuppressive TME through paracrine regulation of Arginase-1 in the myeloid cell population, which includes macrophages and fibroblasts." (PMID 39199680, 2024). "The small-molecular inhibitor CB-1158 that blocks Arg1 enhances immunotherapy in murine models of colorectal tumors, melanoma, and breast cancer and has now been advanced to clinical trials." (PMID 38226622, 2024). "Our results suggest that the infiltration of ARG1-positive cells is an independent prognostic biomarker for poor overall survival in human breast cancer." (PMID 37980483, 2023). "For example, elevated serum/plasma Arg-1 activity was reported to correlate to the extent of metastasis and poor prognosis in breast cancer patients." (PMID 38001706, 2023). "Previous studies have reported that ARG1 is expressed in many types of cancers such as breast cancer and liver cancer." (PMID 36639644, 2023). "In conclusion, this study indicates that ARG1-positive myeloid cells harbour potential as an independent prognostic factor in breast cancer." (PMID 37980483, 2023). "In human breast cancer biopsies, the presence of ARG1-positive cells was strongly correlated with high-grade proliferating tumours, poor prognosis, and low survival." (PMID 37980483, 2023). "In our study, breast cancer cell-derived exosomes induced by ferroptosis decreased the expression of Arg1, indicating that they inhibited M2 macrophage polarization." (PMID 36949762, 2023). "Others reported that Arg-1 expression in breast cancer tissue was positively correlated to better patients’ prognosis, suggesting that Arg-1 plays a tumor-suppressor role." (PMID 38001706, 2023). "A greater proportion of ARG1-positive tumours was observed among special types of breast cancer than among ductal and lobular types (p = 0.03)." (PMID 37980483, 2023). "This indicated that mutations in PRKDC, NOS2, ARG1, and IDO1 were correlated to lower overall survival in breast cancer patients." (PMID 36373232, 2023). "Based on cBioportal analysis, we found that the overall survival time of breast cancer patients with one gene mutation in PRKDC, NOS2, ARG1, or IDO1 was significantly shorter compared with patients without the mutations." (PMID 36373232, 2023). "To address the value of ARG1-positive cells as prognostic markers in breast cancer patients, we performed IHC on 487 biopsies." (PMID 37980483, 2023). "In vitro, TAMs that overexpress ARG1 has a growth-promoting effect on breast cancer cells due to enhanced ARG1 activity and attenuated NO production." (PMID 37426676, 2023).
breast cancer (continued). "The results showed that high expression of ARG1 was detected in colorectal cancer, breast cancer, skin melanoma and other tumors." (PMID 38012650, 2023). "Further, MDSCs and TANs express high levels of S100A9 and the immunosuppressive enzymes IDO and arginase 1 (Arg1) which are specific for their immune-suppressive activity in TME of breast cancer." (PMID 36588678, 2022). "Expression of Arginase1 (Arg1) and Arginosuccinate lyase (Asl) was elevated by 4T1 breast cancer while the mRNA levels of Ornithine carbamoyltransferase (Otc) and Arginosuccinate synthase 1 (Ass1) were reduced." (PMID 35705545, 2022). "Breast cancer cell secreted GM-CSF drove immunosuppression in vitro by increasing MDSC Arg-1 expression thereby inhibiting T cell function, human breast cancer biopsy tissue reflecting this as well." (PMID 36230888, 2022). "High levels of ARG1 have been identified in the serum of preoperative breast cancer patients compared to healthy controls." (PMID 33747948, 2021). "In the CAMP-deficient macrophage group (A438079 pre-treated group), M2 marker ARG-1 expression was decreased when compared to the control group co-culture with breast cancer (BC) cells." (PMID 32365569, 2020). "MDSCs in the PBMCs from patients with breast cancer were enriched in potentially immunosuppressive arginase-1+ cells." (PMID 30254632, 2018). "Western blot hybridization demonstrated that conditioned media from GRP78 inhibition of breast cancer cells reduced the M2 marker, Arg-1." (PMID 29113324, 2017). "The authors found that the level of ARG1 mRNA significantly correlated with higher grades of radiation-induced acute skin toxicities in early breast cancer patients." (PMID 28443095, 2017). "Our data shows a decreased involvement of F4/80-, Arg1- and Ly6G-mediated pathways in our orthotopic breast cancer xenograft model as a result of PLD-specific inhibitor treatment." (PMID 27851813, 2016). "The ability of morphine to reduce arginase-1 expression in IL-4- or 4T1 breast cancer cell-activated macrophages is likely to be beneficial in the context of tumours." (PMID 26078009, 2015). "Primary TAMs isolated from breast cancer tissue produced a large amount of IL-10 and arginase-1, and a small amount of IL-12/23, and exhibited a cluster of differentiation (CD)163high/CD206high phenotype." (PMID 26359357, 2015). "Additionally, the relationship between Arginase-1 (ARG1) and advanced-stage breast cancer was more pronounced than in the early-stage group." (PMID 40665092, 2025). "In terms of the impact on the immune populations in the tumor microenvironment, mammary tumors from PyMT-RONΔMyeloid mice had increased numbers of F4/80 and iNOS positive cells and decreased Arginase-1 positive cells in the tumor TME compared to mammary tumors from PyMT control mice." (PMID 40282397, 2025). "Notably, elevated levels of CASP8, latency-associated peptide of transforming growth factor beta-1 (LAP TGF-β1), HGF, and ARG1 were observed among breast cancer patients diagnosed within 5 years of follow-up." (PMID 40665092, 2025). "TAM-specific extracellular signal-regulated kinase (ERK)/STAT3 activation, increased vascular endothelial growth factor (VEGF) and arginase- 1 (ARG1) production, and HIF- 1a stabilization have all been implicated in lactate-induced TAM polarization and its protumorigenic effects in breast cancer." (PMID 40295451, 2025). "Endocrine-resistant breast cancer cells promote COX-2 expression in TAMs via the JNK/c-Myc/arginase-1 pathway and further promote endocrine resistance in breast cancer cells by activating the PI3K/Akt/mTOR pathway, forming a positive feedback loop between TAMs and breast cancer cells." (PMID 39199574, 2024). "In addition to reducing Arg1 and iNOS expression in MDSCs, doxorubicin similarly suppresses ROS release by MDSCs in breast cancer leading to increased T cell infiltration." (PMID 38464388, 2024).
breast cancer (continued). "Notably, TAMs located in the hypoxic region of murine mammary tumors have been reported to restrict cellular responses through the actions of Arg1 and iNOS." (PMID 39371092, 2024). "The high expression of ARG1 in breast cancer leads to TAM differentiation into the M2 phenotype." (PMID 39192979, 2024). "Using cBioPortal, it was found that PRKDC (DNA‐PK encoding gene) tended to coexist with the functional markers of MDSCs which include NOS2 (iNOS‐encoding gene), Arg1 (Arg1‐encoding gene), and IDO1 (IDO‐encoding gene) in 19 breast cancer studies involving 9134 patients/9555 samples." (PMID 36373232, 2023). "Our results showed that DNA‐PK tended to be co‐expressed with various functional markers of MDSCs (iNOS, Arg1, and IDO), and that the overall survival time of breast cancer patients with mutations of DNA‐PK and various functional markers of MDSCs (iNOS, Arg1, and IDO) was significantly reduced." (PMID 36373232, 2023). "Finally, we performed immunohistochemistry on 487 human breast cancer biopsies and found that the number of ARG1-positive cells correlated with high-grade proliferating tumours, poor prognosis, and low survival." (PMID 37980483, 2023). "ARG1-stained human breast cancer tissues were assessed by bright-field microscopy." (PMID 37980483, 2023). "Besides, the overall survival time of breast cancer patients with at least one gene mutation in PRKDC, NOS2, ARG1, and IDO1 (1191 patients) was significantly shorter compared with patients without the mutations (4575 patients)." (PMID 36373232, 2023). "In addition, ferroptosis-induced breast cancer cell-derived exosomes (Fe-exo) remarkably diminished M2 marker, Arg-1 expression." (PMID 36949762, 2023). "Meanwhile, Arginase-1 (ARG1) and arginase-2 (ARG2), which converted arginine to ornithine and urea, were highly expressed in various tumors such as breast cancer and neuroblastoma, as well as cancer-associated cells such as fibroblasts and myeloid-derived suppressor cells (MDSCs)." (PMID 36798123, 2023). "Importantly, M1 iNOS+ (M1 macrophage marker) staining was elevated while Arginase-1+ staining (M2 macrophage marker) was diminished in the mammary tumors from R7 shNT cells injected into HGFL−/− mice compared to cells transplanted into WT mice." (PMID 35626096, 2022). "In addition, elevated ARG1 is expressed by MDSCs from patients diagnosed with early-stage breast cancer, which is reduced upon surgical tumor resection." (PMID 33747948, 2021). "In a mouse model of early-stage breast cancer, Arg1 was upregulated in TAMs." (PMID 32726950, 2020). "We demonstrated that TNBC cell–derived exosomes are a factor in the induction of M2-type macrophage polarization (upregulation of CD206 and arginase-1) to the benefit of breast cancer cells in vitro and in vivo, supporting enhanced tumor growth and axillary LN metastasis in an orthotopic TNBC model." (PMID 29484119, 2018). "In mouse models of breast cancer, macrophages contribute to tumor progression through a variety of mechanisms including IL-10 and arginase 1 (Arg1)-mediated immunosuppression, MMP 7/9 and CCL18-induced matrix remodeling, and EGF and TNFα-stimulated tumor cell migration and metastasis." (PMID 28881599, 2017). "Arg1 was present in primary mammary tumors and metastatic axillary tumors." (PMID 27851813, 2016). "Similar to RON loss in this model, mammary tumors from PyMT mice with a loss of HGFL show increases in the recruitment of F4/80+ macrophages with increased M1 macrophages marked by iNOS+ staining and a reduction in M2 macrophages marked by Arginase-1+ staining." (PMID 35626096, 2022). "Spatial transcriptomics on these brain metastases revealed that breast cancer cells produce interleukin-34 (IL34), which induces ARG1+ macrophages at the invading edge of metastases." (PMID 42166785, 2026).